IGFBP1 (insulin like growth factor binding protein 1)
Diseases named in the same sentence as IGFBP1 in open-access papers (continued):
Sharing a sentence is not in itself a finding about the gene and the disease.
tumor (continued). "Together, these results illustrate that IGFBP-1 is strongly expressed in tumour tissue, while IGF-1 expression is elevated in normal tissue." (PMID 28143425, 2017). "Our data reveal that IGFBP-1 expression is upregulated in NPC cell lines and NPC tumour tissues and that IGFBP-1 serum levels are elevated in NPC patients." (PMID 28143425, 2017). "Immunostaining of IGFBP-1 was mainly detected in the nuclei of cancer cells and cytoplasm of normal cells, with stronger IGFBP-1 immunostaining present in tumour tissues compared to peritumoural tissues." (PMID 28143425, 2017). "We believed that the feedback regulation loop provided the novel insight into the connection between AMPK signaling and expression of IGFBP1 and also highlighted the tumor suppressor role of AMPKα and IGFBP1." (PMID 27057199, 2016). "IGFBP1 interacts with many proteins and plays an important role in transcriptional regulation and DNA damage repair in tumor development, progression, and resistance to treatment." (PMID 27057199, 2016). "Together, these findings suggested the potential interplay between the tumor suppressors IGFBP1 and FOXO3, and the feedback regulatory axis, resulting in reciprocal pathways that mediated the overall response of UA in HCC cells." (PMID 27036874, 2016). "Our results suggested potential tumor suppressor role of IGFBP1 gene and implied that it can be used as a prognostic marker for NSCLC." (PMID 27057199, 2016). "In the studies mentioned, addition of IGFBP-1 to the control serum reduced tumor cell growth to the same extent as exercise serum." (PMID 23861774, 2013). "Within the top 20 genes ranked by Notch pathway-guided COCA, there are several genes related to differentiation (Tdgf1, Egr1 and Lefty1), cell growth (Ddit4, Hk2, Phlda2, Egln3 and Igfbp1) and tumor/cancer development (Afp, Sfrp2, Egr1, Hk2 and Phlda2)." (PMID 20353603, 2010). "Previous studies have suggested that IGFBP1 may act as a tumor suppressor, although its exact mechanism remains unclear." (PMID 40699800, 2025). "Importantly, the neutralization of secreted IGFBP1 inhibits the confined migration of tumor cells, while the treatment of recombinant IGFBP1 promotes the confined migration." (PMID 37296072, 2023). "Immune infiltration analysis indicated IGFBP1 may inhibit immune cell infiltration in tumors by infiltration and immune escape, leading to tumor metastasis and progression." (PMID 37000073, 2023). "In addition, there are three ways for IGFBP1 to participate in tumor immunity, one is by mediating Cell surface receptor signaling pathway, and the others are by mediating cytokine production pathway or Monocyte signaling pathway." (PMID 37741901, 2023). "In present study, we demonstrate that IGFBP1 is upregulated in tumor cells during confined migration, which promotes ROS scavenging in mitochondria by activating SOD2, mitochondrial Mn‐SOD, thereby supporting the survival of tumor cells during confined migration." (PMID 37296072, 2023). "Similarly, the levels of IGFBP1 protein were also markedly increased in tumor cells during confined migration." (PMID 37296072, 2023). "A potential tumor-suppressor role for miR-519a has also been described in other cancers, but further work is needed to establish whether IGFBP-1 downregulation has a broader role in its actions." (PMID 35597813, 2022). "Insulin resistance-induced alterations in the composition of the IGF family (comprising IGF-1, IGF-2, their receptors, IGF-1R and IGF-2R, and six types of IGF binding proteins (IGFBPs), IGFBP-1 to 6, have been demonstrated to be of key importance in the formation and progression of tumours." (PMID 35328822, 2022). "Notably, HMGA1 is a positive regulator of the IGFs system, with its own DNA binding sites within the IGFBP1 gene promoter, and it is also an inducer of matrix metalloproteinases and other genes involved in tumor invasion." (PMID 36506071, 2022).
tumor (continued). "Some studies have suggested that the anabolic process of IGF-1 and IGFBP1 may make use of substrates such as amino acids to promote tumor development." (PMID 35903696, 2022). "In conclusion, these findings suggested that monocyte acted as a protective factor and MMP9/IGFBP1 played a vital role in tumor immune, which might become potential novel biomarkers and therapeutic targets for immunotherapy in ccRCC." (PMID 33758602, 2021). "Likewise, RXR/RXR and VDR/RXR heterodimers also regulate the expression of IGFBP1, a tumor suppressor gene that was differentially expressed in at least 4 FRCs (IPP, TiBP, TDBPP, TBBPA)." (PMID 33898466, 2021). "Moreover, gene set enrichment analysis revealed that MMP9 and IGFBP1 were involved in tumor immune via mediating cell surface receptor signal pathway, cytokine production pathway, or monocyte signal pathway." (PMID 33758602, 2021). "It has been reported that IGFBP1 plays a dual role in both tumor growth and metastasis 68-70." (PMID 33758602, 2021). "Further bioinformatics analysis revealed that MMP9 and IGFBP1 might act as regulators for monocytes migration and tumor immune." (PMID 33758602, 2021). "A total of 13 paired tumor–normal samples was used in evaluating the expression of IGFBP1." (PMID 34203267, 2021). "HMGA2 and IGFBP1 have been shown to antagonize the tumor-suppressive activity of let-746." (PMID 32651364, 2020). "In addition, by constructing a protein interaction network map, two key modules and 10 key genes were obtained, and the study of IGFBP1 suggested its important position in tumour metastasis." (PMID 33164330, 2020). "Primarily, there is a lack of explicit findings to show that IGFBP-1 evolves tumorigenesis, whereas it is widely taken into account in the regulatory mechanism underlying tumor growth inhibition." (PMID 31752829, 2019). "Importantly, IGFBP-1 expression was stronger in NPC tumour tissues compared to peritumoural tissues." (PMID 28143425, 2017). "Because studies indicate that high levels of MMP9 expression are observed in most NPC tissues, the interaction between MMP9 and IGFBP-1 in NPC tumours may contribute to NPC patients with higher levels of IGFBP-1 and an unfavourable survival." (PMID 28143425, 2017). "Moreover, how IGF-1 and IGFBP-1 are regulated at the expression level remains equivocal in tumour tissues and within the circulating blood stream." (PMID 28143425, 2017). "Consistent with this, our results implied that IGFBP1, acted as a tumor suppressor, could be a potential target in the HCC therapy." (PMID 27036874, 2016). "Animal studies also demonstrated the inhibitory effect of IGFBP1 in tumor growth." (PMID 27057199, 2016). "IGFBP-1 plays a role in promoting the survival and growth of some tumour types 33,34; however, the underlying mechanisms have not been established yet." (PMID 26010680, 2015). "A correlation with internal tumor load was found for IGFBP1." (PMID 23618374, 2013). "Together these studies and our findings suggest that Igfbp1 and Serpina1 may play critical roles in tumor progression in vivo, and are potential candidates for therapeutic interventions." (PMID 18218118, 2008). "According to a previous study, IGFBP1 may decrease tumor growth by blunting the IGF axis." (PMID 40699800, 2025). "The number of subjects in the control and CRC groups to compare the diagnostic value between IGFBP-1 and the classic clinical tumor markers (CEA and CA19-9) was not balanced, which may reduce statistical power." (PMID 38246959, 2024). "Moreover, silencing IGFBP1 expression in microglial cells or neutralizing it with antibodies can reduce the ability of cells to induce angiogenesis, diminishing its involvement in tumor angiogenesis." (PMID 33064893, 2020). "Thus, the true function of IGFBP1 acting as a tumor suppressor or oncogene may depend on the capacity of the context and environment exposed, as well as the cancer type examined, which require further elucidation." (PMID 30209296, 2018).
tumor (continued). "Furthermore, the down-regulation of several proangiogenic factors (uPA, PTX-3, and IGFBP-1) known to foster tumor angiogenesis suggests that NX might indirectly prevent angiogenesis by affecting the tumor microenvironment." (PMID 29156770, 2017). "Insulin-like growth factor (IGF) binding protein 1 (IGFBP1), a pivotal protein of the IGF system, has been shown to be implicated in many cellular functions including proliferation, development, apoptosis, DNA damage repair, and tumor growth through IGF-dependent and -independent mechanisms." (PMID 27036874, 2016). "One study showed that that IGFBP1 may function as a tumor suppressor gene by blunting the IGF axis." (PMID 27036874, 2016). "Thus, a downregulation of IGFBP1 by gastrin may be one mechanism whereby gastrin promotes tumour growth and invasion." (PMID 15846300, 2005). "This study establishes IGFBP1 as a therapeutic nexus connecting m6A-driven NSCLC progression and the anti-tumor effects of Pueraria." (PMID 41818206, 2026). "Analysis of differential expression between GC tumor tissues and normal tissues revealed upregulated SERPINE1, IL1F10, IGFBP1, and ITIH2, whereas C6, GCG, GRP, and APOD were downregulated." (PMID 41551463, 2026). "In brief, IGFBP-1, IGFBP-2, IGFBP-3, and IGFBP-5 have been shown to elevate PD-L1 expression on macrophages and tumor cells, leading to reduced immune response in gliomas, esophageal, and colorectal cancers." (PMID 41226289, 2025). "Integrated characterization of tumor and immune features, a four-gene prognostic signature comprising CD276, MS4A1, IGFBP1, and CD200 was established." (PMID 41488652, 2025). "In renal cell carcinoma, elevated IGFBP-1 correlates with worsened survival and is inversely proportional to CD14 staining in tumor samples, indicating reduced macrophage and monocyte infiltration." (PMID 41226289, 2025). "Mechanistically, secreted IGFBP1 activates mitochondrial superoxide dismutase (SOD2) by preventing AKT1‐mediated SOD2 phosphorylation, thereby promoting metastasis by sustaining tumor cell survival during confined migration." (PMID 37296072, 2023). "It is generally accepted that IGFBP1, IGFBP4, and IGFBP6 inhibit tumor development and progression, and their antitumor activity is mainly ascribable to IGF sequestering." (PMID 37686233, 2023). "Compared to other MMPs, MMP-11 has unique features that may contribute to tumor development and invasion; it is constitutively active and strongly regulates the serine protease inhibitor α1-antitrypsin, insulin-like growth factor binding protein-1 (IGFBP-1), and collagen IV." (PMID 36139587, 2022). "Thus, in the m6A pattern, IGFBP1 may play a significant role in shaping the tumor microenvironment." (PMID 35359993, 2022). "Subsequently, we explored the difference in expression between tumor tissues and adjacent tissues of PAAD and observed that WTAP was notably downregulated in tumor tissues, whereas RBM15, IGFBP1/3, and YTHDF1 seemed upregulated in tumor samples." (PMID 35606813, 2022). "In TCGA data, the average IGFBP1/3/7 expression levels in STAD were significantly higher than those in normal tissue, while IGFBP2/5/6 expression was significantly lower in tumor tissue." (PMID 34745945, 2021). "We found that CTX inhibits tumor-related cytokines, particularly IL-6, IL-8, HGF, TGF-β1, and IGFBP-1." (PMID 34822613, 2021). "IGFBP1/2/4/5/6 are useful prognostic predictors for chemotherapeutic effect in OC patients, and IGFBP2/4 are potential tumor markers for the diagnosis of OC." (PMID 33282953, 2020). "IGFBP-1 expression was detected in the majority of NPC cell lines, but not in NPE cell lines, and was shown to localize to the nucleus of tumour cells, in contrast to the cytoplasmic staining observed in normal cells." (PMID 28143425, 2017).
tumor (continued). "We found that among the IGFBPs studied (IGFBP1–7), IGFBP7 is the only IGFBP down-regulated during tumor progression." (PMID 28882129, 2017). "Consistent with these, UA suppressed tumor growth and increased phosphorylation of p38 MAPK, protein expressions of IGFBP1 and FOXO3a in vivo." (PMID 27036874, 2016). "Our CLM samples showed >97–99% tumor cell homogeneity on IHC, and the mean fold increases in ALDH1A1 and IGFBP1 after normalization to β-actin expression were 6.2 and 3.1, respectively, relative to the adjacent normal liver tissues." (PMID 27152521, 2016). "Chronic exposure to nongenotoxic chemicals such as oxazepam and Wyeth-14,643 increased the expression of IGFBP-1 in a time-dependent manner, and overexpression of IGFBP-1 was also seen in transplacental arsenic-induced HCC and tumor-surrounding tissues." (PMID 15345372, 2004). "Here, we integrated and refined TCGA sourced tumor-related DEGs with genes from TISIDB related to immune to ultimately establish a four-gene prognostic signature comprising CD276, MS4A1, IGFBP1 and CD200, which has the ability to reflect ICIs responses and survival outcomes." (PMID 41488652, 2025). "For example, IGFBP1 and IGFBP2 are closely related to human insulin sensitivity; IGFBP2 may inhibit the effective ways of tumor growth and metastasis." (PMID 37088808, 2023). "In contrast, IGFBP1 depletion did not influence cell apoptosis, cytochrome c release, and caspase 3/7 activation in tumor cells without spatial constraints." (PMID 37296072, 2023). "In addition, we depleted PIEZO1, a well‐established mechanosensitive channel, in tumor cells and observed that PIEZO1 depletion abrogated confinement‐induced upregulation of IGFBP1 mRNA and protein levels." (PMID 37296072, 2023). "To explore the mechanism of IGFBP1‐promoted tumor cell migration, we performed wound healing assay with A549 cells with or without IGFBP1 depletion, which showed that IGFBP1 depletion did not influence the mobility of these cells." (PMID 37296072, 2023). "Comparison of normal and tumor tissue at long-term culture showed increased expression of IGF1R (5-fold, p < 0.0001) and IGFBP6 (3.5-fold, p < 0.01), whereas IGFBP1 (4-fold, p < 0.05), IGFBP3 (2.5-fold, p < 0.01) and IGFBP4 (4-fold, p < 0.01) were downregulated in tumor slices." (PMID 35884847, 2022). "This cluster reduces tumor growth by inhibiting proteins involved in important cellular processes, including homeobox A1 (HOXA1), mammalian target of rapamycin (mTOR), insulin-like growth factor binding protein 1 (IGFBP1), and fibroblast growth factor receptor 3 (FGFR3)." (PMID 35327452, 2022). "It has been reported that M2-type TAMs contribute to the vascular proliferation of GBM cells by releasing insulin-like growth factor binding protein 1 (IGFBP1) and IL-6 to contribute to the expansion of tumor blood vessels in TME and the enhancement of blood supply to tumor tissues." (PMID 35095931, 2021). "MMP11 accelerated the degradation of serine protease inhibitor α1-antitrypsin and insulin-like growth factor binding protein-1 (IGFBP-1), induced differentiation of a desmoplastic reaction surrounding the cancer stroma through cleavage of collagen VI and stimulated tumor progression and metastasis." (PMID 33920789, 2021). "IGFBP1 and IGFBP3 were recognized as tumor suppressor factors in GC." (PMID 33931579, 2021). "In our study, however, IGFBP-1 was mainly observed within the nucleus of cancer cells and in the cytoplasm of normal cells, which is consistent with previous work showing nuclear localization of IGFBP −2, −3 -5, and −6 in tumour cells." (PMID 28143425, 2017). "Despite the lack of sound evidence supporting the stimulation of tumor growth and migration by IGFBP1, the mRNA and protein levels of IGFBP1 were significantly higher in CLM than PCC tissues in our study." (PMID 27152521, 2016).
tumor (continued). "In conclusion, ALDH1A1 and IGFBP1 are differentially overexpressed in CLM and may play a dual role, functioning as both tumor suppressors and metastasis promoters in CRC." (PMID 27152521, 2016). "The TIF secretome was, for the most part, distinctly different from the plasma secretome, although some factors such as TIMP-1, IGFBP-1, PTX3, uPA and IGFBP-3 were observed in both TIF and plasma and may provide plasma biomarkers of the tumor secretome." (PMID 27995973, 2016). "On the whole there is no specific confirmation that IGFBP-1 stimulates tumour growth or it is extensively a tumour growth inhibitor." (PMID 25866791, 2015). "Similar to IGFBP-1, studies examining the prognostic and predictive value of IGFBP-2 as a biomarker are conflicted and require further studies to clarify its value in specific tumor types." (PMID 26217584, 2015). "Of note, IGFBP1 depletion did not influence PIEZO1 expression in confined tumor cells." (PMID 37296072, 2023). "In summary, we speculate that IGFBP1 may cooperate with YTHDF1 to mediate methylation modification, thereby inhibiting the activation of DCs and cytotoxic T lymphocytes, hindering the anti-tumor immune response in tumors." (PMID 35875124, 2022). "Among the other hepatokines investigated in our study, high levels of AHSG, IGFBP1 and IGFBP-2 are found in the serum and HCC tissues of patients, whereas LECT2 expression is usually decreased and appears to behave as a tumour suppressor under the control of beta-catenin in the liver." (PMID 35409319, 2022). "Hepatitis viral infection causes a high level of ROS-induced DNA base damage, increasing the DNA methylation at the promoter of tumour suppressor genes including Cyclin-dependent kinase inhibitor 2A (CDKN2A, or p16), E-cadherin (CDH1), and Insulin-like growth factor binding protein 1 (IGFBP-1)." (PMID 33086505, 2020). "A recent review found that there is a lack of evidence for IGFBP-1 stimulating tumor growth or cell migration, and that it may in fact play a role in tumor growth inhibition." (PMID 27525640, 2017). "Compared to the 10 proteins (GM-CSF, IGFBP-1, IGFBP-3, PTX-3, PDGF-AA, serpin E1, PEDF, TIMP-1, TIMP-4 and uPA) detected in the plasma of MDA-MD-231_WT tumor bearing mice, only 2 (serpin E1 and TIMP-1) were detected in the plasma of MCF-7_WT tumor bearing mice." (PMID 27995973, 2016). "Moreover, we also implanted these cells into randomized NOD/SCID mice by tail vein injection and found that IGFBP1 overexpression dramatically promoted the metastasis of tumor cells rescued with rSOD2 WT, while failed to do so in the cells rescued with rSOD2 S27D." (PMID 37296072, 2023). "IGFBP1 not only regulates the bioavailability and activity of insulin-like stimuli during embryonic development and tumorigenesis, but has also its own biological activity, including the stimulation of tumor cell motility and adhesion, even in the absence of IGFs." (PMID 36506071, 2022). "This study did not primarily focus on tumor heterogeneity, but it is important to recognize that a low MMP-11 immunohistochemical score can be associated with localized MMP-11 expression, which might indicate local progression, through MMP-11 function on substrates like IGFBP1 and Collagen VI." (PMID 38438841, 2024). "We then performed immunoblotting analysis of SOD2 pS27 in confined A549 cells with or without IGFBP1 depletion, showing that IGFBP1 depletion increased SOD2 pS27 in confined tumor cells." (PMID 37296072, 2023). "The results showed that IGFBP1 expression had a weak positive correlation with B cell infiltration, while it had a weak negative correlation with STAD tumor purity, CD8 + T cell, CD4 + T cell, macrophage, neutrophil, and dendritic cell." (PMID 37000073, 2023). "Unlike IGFBP-1 to IGFBP-6, IGFBP-7 inhibits the proliferation of tumor cells by directly binding IGF1R." (PMID 31661774, 2019).